INS (insulin)
Diseases named in the same sentence as INS in open-access papers (continued):
Sharing a sentence is not in itself a finding about the gene and the disease.
diabetes (continued). "NOX inhibitors may improve β‐cell function and enhance insulin sensitivity by lowering ROS levels, thus participates in diabetes management." (PMID 40599237, 2025). "However, in diabetes, the emphasis is on direct effects on glucose metabolism, insulin signaling and beta cell preservation, whereas in cardiovascular disease, the focus is more on vascular protection, lipid metabolism and anti-atherosclerotic actions." (PMID 41009815, 2025). "Based on these findings, we recommend that people with diabetes should consider these plant-based foods in their daily diet, and lifestyle modifications such as regular physical activity along with maintaining a balanced diet will help improve insulin sensitivity and reverse the onset of diabetes." (PMID 40091984, 2025). "Administration of rosiglitazone (4 mg twice daily) along with insulin to obese adults with T1D (average HbA1c 7.9%, BMI 33 kg/m2, diabetes duration 21 years) led to significant reductions in HbA1c, blood pressure, and cholesterol levels, without an increase in insulin requirements." (PMID 39998445, 2025). "Type 1 diabetes mellitus (T1DM), also known as insulin-dependent diabetes, is characterized by the autoimmune destruction of pancreatic beta cells, leading to a complete deficiency of insulin and resulting in chronic hyperglycemia." (PMID 40687580, 2025). "Intestinal endocrine progenitor cells from mice have the potential to be converted into insulin-secreting cells by inhibiting Foxo one or stimulating the expression of Pdx1, MafA, and Ngn3, and can be used as a complementary source in diabetes transplantation therapy." (PMID 40926989, 2025). "Angiotensin converting enzyme (ACE) inhibitor (BF = 0.4286): potential role in blood pressure regulation and cardiovascular protection; dipeptidyl peptidase (DPP)-IV inhibitor (BF = 0.6429): possible application in diabetes management by enhancing insulin regulation." (PMID 40724906, 2025). "Moreover, HoipA-KO mice presented increased blood levels of insulin and HbA1c, a surrogate marker for diabetes onset, upon HFD." (PMID 40961178, 2025). "Maintaining insulin sensitivity through lifestyle modification may be an easier way to prevent diabetes." (PMID 41561051, 2025). "For example, a CER study could assess the impact of insulin therapy versus newer diabetes medications on depression outcomes, while also examining how antidepressants affect glycemic control." (PMID 40003660, 2025). "Also, percent in range and percent out of range are good for people with diabetes who usually have elevated glucose (hyperglycaemia), or who are taking insulin and exhibit hypoglycaemia." (PMID 39715896, 2025). "Notably, patients with diabetes show elevated levels of TSC22D4 expression in the liver, linked to reduced insulin sensitivity, high blood sugar levels, and lower LCN13 serum concentrations." (PMID 39906612, 2025). "The mechanism by which triglycerides (TGs) affect diabetes mellitus combined with hyperuricemia may be related to its role in inflammation, oxidative stress and insulin signaling, which may affect glucose metabolism and insulin resistance." (PMID 41322694, 2025). "Overall, icodec is a useful, new formulation of basal insulin that allows for less injections, improved compliance, and potentially improved glycemic control providing a new tool to practitioners managing patients with diabetes who need to be on insulin." (PMID 40156735, 2025). "Another chalcone named 2′, 6′-dihydroxy-4′-methoxychalcone was described to prominently lesser the blood glucose levels in streptozotocin-induced diabetes rats model suppression of enzymes including protein tyrosine phosphatase 1B, α-glucosidase aldose reductase, and increased secretion of insulin." (PMID 40599794, 2025). "ICI-related diabetes is irreversible, and the patients require life-long insulin treatment." (PMID 40729244, 2025).
diabetes (continued). "The higher diabetes prevalence among male stroke patients (45.2% vs. 38.7% in females) may reflect sex-specific differences in insulin sensitivity and glucose metabolism." (PMID 40969369, 2025). "Diabetes is a systemic metabolic disorder characterized by elevated blood glucose levels, known as hyperglycemia, resulting from defects in insulin secretion, insulin action, or both." (PMID 41008312, 2025). "This is why insulin extracted from pigs and cows was successfully used to treat diabetes in millions of people for over 60 years before scientists could make perfect human insulin in labs (Johnson 1983, Schernthaner 1993)." (PMID 40917652, 2025). "This process results in insufficient insulin secretion and the development of diabetes." (PMID 41185072, 2025). "Consequently, a state marked by moderate, stable hyperglycemia with 40% reduction in β-cell mass and substantial depletion (60%) of pancreatic insulin reserves is established, which exhibits diabetes-related symptoms, including polyphagia and polydipsia." (PMID 41227734, 2025). "Historically, the usage of CGM for inpatient diabetes management has raised concerns about insulin stacking due to the all-time available glycemic data and subsequent hypoglycemia or a state of clinical inertia due to a lack of operational algorithms on how to act on CGM data." (PMID 40980547, 2025). "In patients with diabetes, alterations in K+ channels commonly manifest in several ways: 1) K+ channel gene mutations, which serve as a significant contributor to monogenic diabetes, leading to impaired β-cell insulin secretion and subsequent diabetes development." (PMID 40650956, 2025). "However, in our study, this increase in insulin sensitivity was insufficient to restore glucose homeostasis or reduce the need for diabetes therapy." (PMID 40205383, 2025). "Two of her siblings were also diagnosed with diabetes at the age of 8 and were insulin dependent." (PMID 39717432, 2025). "Its role in metabolic regulation-by improving insulin sensitivity, regulating lipid metabolism, and controlling energy expenditure-suggests it could be used to manage conditions like diabetes and obesity, which are major contributors to CKM." (PMID 39781722, 2025). "In the context of diabetes mellitus, inhibiting METTL3 activity has been shown to diminish the m6A modification levels of genes associated with insulin resistance, consequently enhancing insulin sensitivity." (PMID 40066222, 2025). "One promising strategy for PERT dosing is, instead of fixed dosing, using a ratio similar to the insulin-to-carb ratio, a concept which may be familiar and comfortable to people living with diabetes who have EPI." (PMID 40807043, 2025). "By overcoming the current limitations, these biocompatible and biodegradable materials could pave the way for more efficient, patient-friendly insulin therapies in the future, offering improved blood glucose management for individuals with diabetes." (PMID 40352348, 2025). "Additionally, studies on human pancreatic cells have indicated that extracts from can protect β‐cells from oxidative damage, which is one of the common presentations of diabetes, and augment insulin secretion." (PMID 40842670, 2025). "Interestingly, we observed a relationship between SAT density with glucose and HbA1c levels, as well as overall diabetes status, while VAT density was associated with insulin levels and HOMA-IR scores." (PMID 40533477, 2025). "While conventional antidiabetic therapies such as metformin, sulfonylureas, insulin, GLP-1 receptor agonists, and SGLT-2 inhibitors have been reported to be effective in managing diabetes, they are unfortunately associated with several limitations and health-related side effects." (PMID 41463330, 2025). "This study aimed to estimate how these newer medications could help reduce insulin needs and improve health outcomes for people with diabetes in LMICs." (PMID 40245017, 2025).
diabetes (continued). "Restoration of Cav-3 expression or inhibition of its nitration rescues insulin signaling and provides protection against diabetes-induced ischemic heart failure, underscoring the importance of maintaining caveolae integrity for preserving insulin sensitivity in cardiac tissues." (PMID 40358155, 2025). "In glucose‐stimulated insulin secretion in mouse and human islets, d‐Cys inhibited insulin secretion more than d‐Ser; in mouse models of diabetes and non‐obese diabetes, as well as in the human pancreas, the diabetic state was characterized by high d‐Cys and SR expression levels." (PMID 40146632, 2025). "Similarly, one small observational study showed reduction or cessation of insulin use in 5/9 patients with pre‐existing diabetes post‐transplant once corticosteroids stopped." (PMID 40664615, 2025). "Type 2 diabetes mellitus (T2DM) is closely associated with aging and leads to abnormalities in glucose‐lipid metabolism and hepatic insulin pathways." (PMID 40336535, 2025). "The potential role of cg22363520 in regulating inflammatory processes suggests that it may contribute to diabetes development through mechanisms involving insulin resistance and β-cell dysfunction." (PMID 40017583, 2025). "Findings from this study may contribute to the development of more personalized dietary strategies for diabetes management, particularly in a subgroup of patients with severely impaired insulin secretion." (PMID 41586239, 2025). "However, we believe that with the help of nurses trained in diabetes education, many more children with diabetes will be able to benefit from insulin pump prescriptions." (PMID 40724118, 2025). "Additionally, prolonged diabetes duration enhances renin–angiotensin–aldosterone system (RAAS) activity while reducing insulin-mediated vasodilation, further contributing to elevated blood pressure." (PMID 40822947, 2025). "Current pharmacologic treatments for diabetes mellitus regulate blood glucose through various mechanisms, including stimulating insulin secretion, inhibiting carbohydrate absorption, promoting urinary glucose excretion, and enhancing insulin sensitivity." (PMID 41383475, 2025). "The gut microbiota and its metabolites can influence insulin sensitivity, and a well-balanced microbiota ecosystem may contribute to the alleviation of diabetes." (PMID 40019272, 2025). "The diabetic rats also showed elevated oxidative stress, indicating that the mitochondrial dysfunction caused by the variation, coupled with the metabolic strain of the diet, led to increased oxidative stress, impairing insulin secretion and contributing to diabetes development." (PMID 39835172, 2025). "However, its use in lean diabetes with insulin secretory defects is inappropriate, and its impact has never been explored." (PMID 40995598, 2025). "Additionally, we did not categorise the T2DM group based on the presence of complications, duration of diabetes, or insulin intake." (PMID 40951890, 2025). "Diabetes is a disease with an extremely high incidence rate, and 90–95% of cases are classified as Type 2 diabetes mellitus (T2DM), characterized by a progressive loss of insulin secretion in β-cells following the development of insulin resistance." (PMID 41354800, 2025). "Of the patients with diabetes mellitus, 29.1% were treated with metformin and 51.9% with insulin." (PMID 39913415, 2025). "We analysed this further and separately assessed cancer incidence in participants with known type 2 diabetes (already using glucose-lowering medication and/or insulin) and those with screen-detected diabetes, e.g. those with elevated fasting blood glucose or HbA1c at baseline Lifelines screening." (PMID 40859200, 2025). "The large effect sizes suggest substantial therapeutic benefits that may contribute to better diabetes management, as chronic stress is known to impair glucose regulation and insulin sensitivity." (PMID 41293201, 2025).
diabetes (continued). "Among this diverse disease set, diabetes is associated with chronic hyperglycemia which is the main consequence of lack of insulin (type 1 diabetes, T1D) or loss of the insulin production correlated with the insulin resistance (type 2 diabetes, T2D)." (PMID 40259265, 2025). "Levels between 200 and 600 pmol/L (fasting threshold 80–250 pmol/L) are likely to correlate with T1D or monogenic diabetes but may also occur in insulin‐treated T2D." (PMID 39797595, 2025). "Diabetes is characterized by an increase in glucose levels in the blood, which occurs due to the inability of the pancreas, through a combination of genetic and environmental factors, to produce enough insulin to meet the body’s demands." (PMID 40324160, 2025). "There are many types and forms of diabetes mellitus, the main classification criterion being the cause and mechanisms of production, resulting in type 1 diabetes mellitus (insulin-dependent), type 2 diabetes mellitus—T2DM (non-insulin-dependent), gestational diabetes mellitus, and hybrid forms." (PMID 41020831, 2025). "T1DE presents with difficulties in diabetes self-care behaviours, which can include deliberate insulin omission or restriction, low-carbohydrate diets to reduce insulin requirements or blood glucose fluctuations, and episodes of binge eating in response to hypoglycaemia symptoms." (PMID 39902232, 2025). "However for the insulin user in the mainstream of care (ambulatory diabetes services in primary and secondary care) the broad principles of choice and management of insulin therapy are fairly easily applied." (PMID 40035222, 2025). "Confirming the obtained results, some studies suggest that diabetes may lead to hormonal imbalances by affecting luteal secretion and insulin sensitivity, which can increase progesterone levels." (PMID 40299518, 2025). "Furthermore, this technology supports long-term diabetes care by informing adjustments to insulin, diet, and exercise regimens." (PMID 40053775, 2025). "Similarly, regular physical activity enhances insulin sensitivity and glycemic control, which in turn mitigates the pro-inflammatory and atherogenic effects of diabetes." (PMID 40606517, 2025). "This inverse relationship suggests that these miRNAs may suppress critical components of glucose metabolism and insulin signaling, contributing to systemic metabolic dysregulation observed in diabetes." (PMID 41208460, 2025). "A composite approach that combines therapies targeting SLC7 transporters with established treatments for diabetes—like insulin sensitizers and drugs that lower glucose levels—might produce compounded benefits." (PMID 40469683, 2025). "Initiation of subcutaneous insulin is recommended only when blood glucose levels have fallen to <200 mg/dL, and the patient demonstrates clear resolution of ketoacidosis, indicated by normalized anion gap, pH of >7.3, bicarbonate of >15-18 mEq/L, and absence of ketonemia." (PMID 41141170, 2025). "Additionally, in patients with diabetes or obesity, vitamin D supplementation has shown modest improvements in insulin sensitivity and inflammatory control, suggesting a potential role in mitigating metabolic and vascular stress." (PMID 40362848, 2025). "Conventionally, insulin has been the main treatment for diabetes in patients with liver cirrhosis." (PMID 40704640, 2025). "A longstanding question in diabetes research is whether beta cell dysfunction represents an initiating defect in type 2 diabetes or whether it emerges in response to insulin hypersecretion." (PMID 40768044, 2025). "Type 1 diabetes mellitus (T1DM) is an autoimmune disease accompanied by progressive destruction of β-cells in pancreatic islets, which leads to the loss of endogenous insulin secretion, hyperglycemia, and lifelong dependence of the patients on exogenous insulin administration." (PMID 40979707, 2025). "The use of insulin as a treatment for diabetes mellitus has been marred by several challenges." (PMID 41155876, 2025).
diabetes (continued). "Insulin resistance is very common in the population with obesity, diabetes and metabolic syndrome, which may increase the risk of thyroid cancer via the activation of the IGF pathway and the insulin pathway." (PMID 40535346, 2025). "“Once the old man went out to eat with me, I have diabetes and have to take insulin." (PMID 40924672, 2025). "By blocking MSTN action, these inhibitors could enhance muscle growth, increase energy expenditure, and improve insulin sensitivity, offering a promising approach to combating diabetes-related health conditions." (PMID 39340593, 2025). "Women using “insulin only” had a higher all-cause mortality risk compared to women without diabetes, whereas women in the subgroups “non-insulin GLD only” and “insulin and non-insulin GLD” subgroups had a lower all-cause mortality risk." (PMID 41350985, 2025). "Furthermore, HOMA-IR score (which combines insulin and glucose level) and history of diabetes are among the two most influential indicators for early GDM detection." (PMID 40082942, 2025). "Carbohydrate type, age, and insulin sensitivity shape glycemic responses in diabetes." (PMID 40507211, 2025). "Therefore, assessment of insulin secretory capacity is instrumental in classifying diabetes types and guiding treatment strategies." (PMID 41225468, 2025). "Finally, the mechanisms of iron in diabetes are thoroughly studied, including the impact on glycemic control and the roles of iron status and iron metabolism related genes in insulin regulation." (PMID 40871742, 2025). "It is important to note that pharmacological conversion of exocrine pancreatic cells, gastric stem cells, intestinal epithelial cells, or gut endocrine progenitors into insulin-producing cells may offer a promising perspective for diabetes therapy." (PMID 40497986, 2025). "Similarly, PP infusion in patients with type 1 or pancreatogenic diabetes on insulin pump therapy enhanced insulin sensitivity and reduced the insulin dose needed to maintain normal glucose levels." (PMID 40214973, 2025). "The average age of the children on behalf of whom the interviews were completed was 12.0 ± 5.2 years, 67% were female, and the majority had favorable HbA1c values and were using a CGM and automated insulin delivery (AID) system (similar to the statistics seen in our Diabetes Program)." (PMID 41276018, 2025). "Consequently, transplantation of vascularized islet organoids with enhanced insulin secretion capacity remains essential for sustainable diabetes management." (PMID 41301178, 2025). "The central features of diabetes are chronic inflammation and peripheral insulin resistance; accumulating evidence indicated that SCFAs could improve insulin sensitivity and prevent inflammation in in vivo and in vitro models of diabetes." (PMID 40697558, 2025). "However, the ISR group had a significantly higher proportion of patients on insulin therapy (64.5% vs. 46.6%, p = 0.01), indicating more advanced or poorly controlled diabetes in this subgroup." (PMID 40978996, 2025). "Meanwhile, because of the low eGI, the triticale noodles enriched with SP may be more beneficial for those who control their postprandial blood sugar, such as diabetics and insulin-resistant subjects." (PMID 40647034, 2025). "Moreover, in patients with diabetes, chronic hyperglycemia impairs the body’s responsiveness to insulin and reduces sensitivity to acute glucose variations." (PMID 41458546, 2025). "“My daughter feels bad because she tells me that the children don’t know what diabetes is and why she has to take insulin... if there was a nurse in the school, she could also help her to do this”." (PMID 39997793, 2025). "The proposition that obesity could drive malnutrition status in patients with HF and diabetes involves several physiological mechanisms, such as skeletal muscle insulin resistance, altered lipoprotein profile and low‐grade inflammation." (PMID 40074368, 2025).